IL33 (interleukin 33)
Diseases named in the same sentence as IL33 in open-access papers (continued):
Sharing a sentence is not in itself a finding about the gene and the disease.
dermatitis (continued). "Epithelial-specific IL-33 transgenic mice have been found to develop AD-like dermatitis, including acanthosis, pruritus, increased IgE serum levels, reduced claudin-1 expression, and increased production of eosinophils, mast cells, and ILCs33,34." (PMID 32792500, 2020). "In conclusion, the present study demonstrates that QRQS regulates the related molecular expression of ovalbumin-induced dermatitis involved in the IL-33/ST2 signaling axis in the treatment of acute AD." (PMID 28751921, 2017). "QRQS decreased both epidermal and dermal thickness, alleviated dermatitis, and reduced IL-33 and ST2 positive cell numbers." (PMID 28751921, 2017). "QRQS regulates related molecule expression of ovalbumin-induced dermatitis involved in the IL-33/ST2 signaling axis in the treatment of acute AD." (PMID 28751921, 2017). "In summary, secreted mmIL-33 itself has a potent capacity in skin inflammation whereas fl IL-33 is limited due to its intracellular retention." (PMID 28702024, 2017). "In order to assess the role of IL-33 in skin inflammation, we developed transgenic mice that expressed the full-length mouse IL-33 under the control of a human K14 promoter via pronuclear injection of K14-IL-33 construct (hK14mIL33tg)." (PMID 28702024, 2017). "With induction of maturated IL-33 in the skin of K14-mmIL-33 mice, cytokines responsible for skin inflammation were upregulated." (PMID 28702024, 2017). "Here, we demonstrated that IL-33 has the potential to induce skin inflammation with high potency if present in its mature form." (PMID 28702024, 2017). "Here, we wanted to elucidate the role of IL-33 in skin inflammation using different IL-33 expression models." (PMID 28702024, 2017). "The interleukin (IL)-1 family member IL-33 has been described as intracellular alarmin with broad roles in wound healing, skin inflammation but also autoimmunity." (PMID 28702024, 2017). "Since IL-33 levels vary depending on the tissue and are differently regulated between health and disease more studies are needed to elucidate its role in skin inflammation." (PMID 28702024, 2017). "IL-25 and IL-33 are overexpressed in skin of patients with AD,16, 49, 50, 51 with TSLP overexpression associated with skin inflammation in mice." (PMID 26299987, 2016). "Together with previous reports on the participation of IL-31 in pruritus and dermatitis in animal models and IL-33 in AD, our results provide insight of the pathological roles of IL-31 and IL-33 in the pathogenesis of AD." (PMID 22272250, 2012). "Moreover, the induction of dermatitis resembling AD was observed in a transgenic mouse model characterized by the overexpression of IL‐33 in the skin." (PMID 39654684, 2024). "Additionally, propionate, a metabolic product of sebum, suppressed skin inflammation in a calcipotriol (MC903), a calcium analog of vitamin D3, -induced AD-like dermatitis mouse model by inhibiting IL-33 production in keratinocytes." (PMID 38590314, 2024). "However, in Kitwsh/wsh mice, the exacerbating effect of IL-33 was blocked, but skin inflammation severity scores in this group increased from Day 5 compared to the control group, although without statistical significance." (PMID 36894987, 2023). "Reduction in IL-33 production by keratinocytes and attenuation of skin inflammation." (PMID 37509136, 2023). "Because AD patients exhibit a decreased production of sebum and its microbial metabolite, propionate, a recent study has shown that topical propionate application attenuates skin inflammation in mice with MC903-induced AD-like dermatitis by inhibiting IL-33 production in keratinocytes." (PMID 37509136, 2023). "The mediators involved in Th2 reactions include IL-4, IL-5, IL-13, IL-33, and IgE, in which IL-4 triggers dermatitis, similar to its effect in AD by inhibiting the production of IFN-gamma, thereby inducing an immune imbalance and increasing the synthesis of IgE." (PMID 36077570, 2022).
dermatitis (continued). "The migration of ILC2 has not been investigated in inflammatory conditions of dermatitis caused by excess IL-33." (PMID 34909732, 2021). "One of these, miR-155-5p, when blocked, leads to a higher production of filaggrin, lesser production of TSLP and IL-33, which is another interleukin involved in this form of dermatosis, and a strengthening of tight junctions among cells via upregulation of occludin." (PMID 34944487, 2021). "Since previous work showed that basophils expressed ST2 and were required for initiating skin inflammation in a chronic allergic skin model that included a strong neutrophil component, we hypothesized that basophils might be sensing mast cell–derived IL-33." (PMID 31940364, 2020). "The localized actions of IL-33 on ILC2 activity were demonstrated in mice with skin-specific overexpression of IL-33 develop spontaneous dermatitis with increased ILC2 numbers; however, a conflicting report demonstrated that skin ILC2 activation is critically dependent on TSLP signaling." (PMID 31574995, 2019). "Previous studies have shown that interleukin-33 (IL-33) is highly expressed in skin keratinocytes and endothelial cells, and its effect on the skin may be related to the early stage of skin inflammation and AD." (PMID 28751921, 2017). "A mouse model with local overexpression of IL-33 in keratinocytes led to Th2 induced dermatitis." (PMID 28702024, 2017). "We found that the IL-33 promotor was active within the joints of mice during CIA, so we wondered whether IL-33 was expressed in the skin during IMQ-induced skin inflammation in mice." (PMID 27317338, 2016). "In addition, the skin of MC903-induced dermatitis model mice showed increased expression of Il33." (PMID 37298299, 2023). "We therefore decided to investigate the function of the IL-33/ST2 signaling system by backcrossing single- and double-deficient mutants of ligand and receptor to the same genetic background (C57BL/6J BomTac) and comparing their response to calcipotriol-induced dermatitis." (PMID 32296080, 2020). "Therefore, blockage of IL-33/ST2 signaling may represent a therapeutic target to relieve pruritus and skin inflammation of IL-33/ST2 signaling-related dermatitis." (PMID 30886621, 2019). "We therefore aimed to elucidate whether a local inflammatory stimulus was sufficient to release and activate full-length IL-33 in the hK14mIL33tg mouse and performed different skin inflammation models including rIL-23 ear injection, topical IMQ, and barrier disruption using skin tape stripping." (PMID 28702024, 2017). "Mirroring murine models, human skin ILC2s can be activated by IL-25, IL-33, and TSLP, with high expression of IL-33 and TSLP during chronic skin inflammation." (PMID 35359972, 2022). "In a murine study, the central role of IL-33/ST2 signaling in pruritus and skin inflammation of this ACD has been illustrated, and the pruritic mechanism is associated with the interaction of IL-33/ST2 signaling with primary sensory neurons." (PMID 30886621, 2019). "Critically, MrgprA3 neuron stimulation in mice lacking myeloid-IL-33 fails to enhance skin inflammation or anti-helminth resistance, implying that MrgprA3 neurogenic inflammation is mechanistically linked to suppression of myeloid-intrinsic IL-33." (PMID 38076920, 2023). "We noticed that that HB inhibits DNCB-induced IL-33 and ST2 mRNA levels in dermatitis skin tissue." (PMID 34531749, 2021). "Moreover, AD patients and mice with AD-like dermatitis have increased IL-33 and ST2 levels, and transgenic mice that selectively overexpress IL-33 in keratinocytes develop an AD-like disease." (PMID 32296080, 2020). "We addressed contribution of other IL‐1 cytokine family members to spontaneous skin inflammation in Flgft/ft mice but development of dermatitis in Flgft/ft mice was independent of IL‐33, IL‐18, and IL‐36." (PMID 30937919, 2019).
dermatitis (continued). "Therefore, we identified a critical role of IL-33 signaling via ST2 and uncovered the pivotal function of MyD88 in DCs in MC903-induced AD-like skin inflammation." (PMID 28383552, 2017). "Our results show that IL-33 is expressed at a higher level in keratinocyte nuclei in the epidermis of the depilatory cream-treated dorsal skin of TG mice even without any visible skin inflammation compared to the depilatory cream-treated dorsal skin WT mice." (PMID 39201426, 2024). "Moreover, IL-33 produced by epidermal keratinocytes can induce ILC2 production from skin tissues and lymph nodes, which further stimulates IL-5 release and induces the occurrence of AD-like dermatitis." (PMID 34925005, 2021). "This suggests that keratinocyte damage in the absence of SHARPIN may lead to release of TSLP and IL33, which initiate the dermatitis through the activation of ILC2 and basophils." (PMID 32687504, 2020). "Importantly, both St2–/–and Il33–/–mice remained capable of eliciting local skin inflammation in response to the non-specific, mast cell–independent irritant croton oil." (PMID 31940364, 2020). "Severe dermatitis induced by repeated DNFB-application under SPF condition in NC/Nga was alleviated partially in NC.h2b/nc and significantly in NC.h2b/b as shown by decreased epidermal expression levels of TSLP and serum levels of total IgE, TSLP, IL-18 and IL-33." (PMID 29416104, 2018). "Since in our described model, no IL-33-dependent exacerbation of skin inflammation was observed, we hypothesized that an additional signal is necessary for externalization and action of fl IL-33." (PMID 28702024, 2017). "Thus, despite different immunological provocations no phenotype of full length (fl) IL-33 overexpression could be observed, which showed that skin inflammation per se does not promote action of IL-33." (PMID 28702024, 2017). "MC903-induced dermatitis was dependent on thymic stromal lymphopoietin (TSLP), IL-25 and IL-33 in BALB/c mice, and on TSLP, but not IL-25 or IL-33, in C57BL/6 mice." (PMID 35874756, 2022). "Our findings indicate that lack of interleukin-33 and its receptor ST2 does not prevent the development of AD-like skin inflammation." (PMID 32296080, 2020).
allergic rhinitis (55 papers, 2010 to 2026). Inflammation of the nasal mucous membranes caused by an IgE-mediated response to external allergens. "We identified protective effects for IL33 for hayfever (coded hayfever/allergic rhinitis), nasal polyps, and angina as well as weak risk effects for bowel/intestinal obstruction and shoulder/scapula fracture." (PMID 29691392, 2018). "The same group reported the association of serum levels of IL33 and SNPs in the IL33 gene with Japanese cedar pollinosis, the most common form of allergic rhinitis in Japan." (PMID 21629437, 2010). "IL-33 is closely associated with allergic rhinitis, and interfering with IL-33 may be a new modality for the treatment of allergic rhinitis." (PMID 39301028, 2024). "Additionally, baseline IL-33 mRNA levels were strongly associated with late allergic reactions (LAR) in allergic rhinitis, as revealed in studies investigating the molecular basis of LAR." (PMID 39301028, 2024). "In the patients with seasonal allergic rhinitis, the serum level of IL-33 was found to be significantly increased and there is a significant association between susceptibility to allergic rhinitis and IL-33 polymorphism." (PMID 36291105, 2022). "In a mouse model of allergic rhinitis, treatment with anti-IL-33 significantly reduced nose scratching events, brought about an apparent improvement in skin exfoliation symptoms, and diminished the degree of eosinophil infiltration." (PMID 40429652, 2025). "In the realm of allergic rhinitis (AR) research, the anti-IL-33 therapy has demonstrated remarkable efficacy in AR animal models." (PMID 40429652, 2025). "In an experimental allergic rhinitis mouse model, it was shown that IL-33 protein was constitutively expressed in the nucleus of nasal epithelial cells and was promptly released in response to nasal exposure to ragweed pollen." (PMID 38398010, 2024). "The allergic rhinitis animal study found that serum IL-33 levels and nasal mucosal oxidative stress significantly increased in the OVA + DEHP group than those in the OVA group." (PMID 37545493, 2023). "Allergic rhinitis (AR) is characterized by airway inflammation in nasal mucosa from inhaled allergens and interleukin (IL)-33 is the potent inducer of Th2 inflammation in allergic nasal epithelium." (PMID 37237381, 2023). "Studies on the levels of alarmins in patients with allergic rhinitis have shown that levels of IL-33, IL-25, and TSLP are significantly higher compared to healthy controls." (PMID 35406669, 2022). "Adjusted and unadjusted logistic regression analyses suggested that comorbid allergic rhinitis, B-EOS percentages, T-EOS counts and percentages, and serum sST2 and IL-33 levels were associated with postoperative recurrence (P < 0.05)." (PMID 35633657, 2022). "The elevated serum level of IL-33 not only induces the inflammatory response, but also its concentration is positively correlated with allergic rhinitis severity." (PMID 36291105, 2022). "The serum level of IL-33 was studied in a large group of patients suffering from allergic rhinitis sensitive to Japanese cedar." (PMID 22349136, 2012). "Taken together, the results of our study and previously published papers confirm the role of IL-33 in Th2-mediated diseases, such as intermittent allergic rhinitis." (PMID 22349136, 2012). "In conclusion, we found elevated levels of IL-33 in sera of patients with intermittent allergic rhinitis sensitive to tree and/or grass pollen, and that the serum level of IL-33 correlated with the disease severity." (PMID 22349136, 2012). "Elevated level of IL-33 in sera of patients with IAR sensitive to tree and/or grass pollen and the correlation of IL-33 with the disease severity suggest that IL-33 is involved in the pathogenesis of intermittent allergic rhinitis." (PMID 22349136, 2012). "In addition to this, genetic factors including cytokine genes influence IL-33 levels and also play an important role in allergic rhinitis." (PMID 39301028, 2024).
allergic rhinitis (continued). "We also observed whether the difference of CB IL-33 levels in different clusters including maternal allergic history, pets or not, second-hand smoking exposure during pregnancy, and the severity of allergic rhinitis in child." (PMID 37545493, 2023). "The level of IL-33 has been correlated with the severity of allergic rhinitis." (PMID 36644088, 2022). "Additionally, one report has shown that IL-33 is activated by GM-CSF and IL-8 in the nasal mucosal epithelium of allergic rhinitis." (PMID 31817806, 2019). "Quantitative RT-PCR analysis showed that the expression levels of Il4, a key mediator of Th2 response, and of the Il33 gene, which is necessary for the development of allergic rhinitis, were reduced in the lungs of Mlys-IL-6 KO mice as compared to WT control mice." (PMID 30534125, 2018). "Our results suggest that IL-33 is involved in the pathogenesis of intermittent allergic rhinitis." (PMID 22349136, 2012). "Interestingly, it has been shown recently that anti-IL-33 antibody has a therapeutic potential for experimental allergic rhinitis in a murine model of nasal allergy." (PMID 22349136, 2012). "In addition, studies have shown that IL-33 could inhibit ST2/PI3K/mTOR mediated autophagy in allergic rhinitis; It also provided neuroprotection by inhibiting autophagy." (PMID 37081450, 2023). "Recent studies suggest that inhibiting ILC2s through the IL-33/ST2 and JAK/STAT pathways can alleviate type 2 inflammation in OVA-induced allergic rhinitis." (PMID 40230853, 2025). "These also suggest that the involvement of IL-33/ST2 axis in the type 2 response is different from the typical Th2 cytokines such as IL-4, IL-5, and IL-13 in terms of its independent role in allergic rhinitis." (PMID 36291105, 2022). "Airway epithelium plays an important role during the development of allergic rhinitis (AR), which is characterized by production of thymic stromal lymphopoietin (TSLP), interleukin 33 (IL-33), and interleukin 25 (IL-25)." (PMID 34899052, 2021). "Airway ILC2s express far more ST2 than IL-17RB, and while both IL-33 and IL-25 are produced by nasal epithelial cells during HDM-induced allergic rhinitis, defects in eosinophil and goblet cell counts are seen only in IL-33−/− and not IL-25−/− mice." (PMID 41409758, 2025). "IL-33 also seems to be essential for development of allergic rhinitis induced by ragweed pollen challenge as IL-33 knockout mice failed to induce ragweed pollen induce allergic rhinitis." (PMID 26425339, 2015). "The serum level of IL-33 was found to be higher in patients with Japanese cedar pollinosis, However, it has not been studied in intermittent allergic rhinitis in patients allergic to other allergens." (PMID 22349136, 2012). "We therefore decided to analyze the serum level of IL-33 and the soluble form of its receptor ST2 in patients with intermittent allergic rhinitis sensitive to grass and/or tree pollen and to compare with results in bronchial asthma patients and healthy controls." (PMID 22349136, 2012). "However, there are less data on the role of IL-33 and its receptor ST2 in intermittent allergic rhinitis." (PMID 22349136, 2012). "For example, interleukin-33 (IL-33), produced by epithelial cells, could stimulate mast cells to secrete histamine, which is the main mediator that stimulates nasal rubbing and sneezing in ovalbumin (OVA) induced allergic rhinitis (AR)." (PMID 35269483, 2022). "However, the precise roles of IL-33 and IL-25 in house dust mite (HDM)-induced allergic rhinitis (AR) remain unclear." (PMID 24205109, 2013). "However, the specific role of IL-33 and its receptor ST2 in allergic rhinitis remains unclear." (PMID 39301028, 2024). "Similarly, IL33 mRNA expression could be induced by IFN-γ, the TLR9 ligand ODN2006, or polyI:C but not LPS in human nasal epithelial cells with allergic rhinitis." (PMID 27826297, 2016).